CD69 (CD69 molecule)
Diseases named in the same sentence as CD69 in open-access papers (continued):
Sharing a sentence is not in itself a finding about the gene and the disease.
lymphoma (14 papers, 2006 to 2025). A malignant (clonal) proliferation of B- lymphocytes or T- lymphocytes which involves the lymph nodes, bone marrow and/or extranodal sites. "CD69 immunoreactivity was present in 95 % of the lymphoma tissue samples and in 70 % of the stroma samples." (PMID 25773455, 2015). "The resulting two independently derived transgenic mice expressed the transgene and developed a metastasic, angiogenic and transplantable CD4+CD8+CD69– lymphoma." (PMID 22558084, 2012). "Namely, after stimulation with epitope pulsed HLA matched lymphoma cells only a proportion (up to 70%) of CD69+ cells in an EBNA1 specific Th1 CD4+ T cell clone can be visualized by intracellular IFN-γ staining." (PMID 21429247, 2011). "Importantly, decreased CD69 levels on lymphoma cells have previously been found in more Th2-skewed CTCL lesions, a phenotype associated with progressing disease." (PMID 34583709, 2021). "(F) Flow cytometric analysis of S1PR1 surface expression on WEHI231 lymphoma cells transduced with S1PR1 and CD69 wild-type and mutant constructs as indicated." (PMID 37039481, 2023). "We observed some indication of bystander T cell activation as CAR− cells seemed to upregulate CD69 and TIM-3 upon co-culture with LOAd703-infected lymphoma cells." (PMID 33666760, 2021). "Likewise, the activation markers CD107a, CD69 and 4-1BB were highly upregulated on CAR+ T cells in the presence of lymphoma cells in general, but CD107a expression was only significantly upregulated with LOAd703." (PMID 33666760, 2021). "The absence of CD69 expression in the lymphoma suggests that the transformation event took place prior to positive selection." (PMID 22558084, 2012). "In contrast, antigen negatively selected lymphomas from wild type recipients (WT), failed to induce CD69 and expansion of CD8+ (OT-I) T-cells, and continued to proliferate in coculture." (PMID 22479645, 2012). "MMTV-RARαG303E lymphomas were high grade Pax-5+, surface H+L Ig negative, CD69+ and BCL6- and cytologically and phenotypically resembled human adult high grade (Burkitt's or lymphoblastic) lymphomas." (PMID 16563162, 2006). "Consistently, lymphomas were Pax5+, B220+, CD43+, AA41+, CD69+ and negative for surface heavy or light chain immunoglobulins, CD5, CD4, CD8, CD23, CD21, BCL6." (PMID 16563162, 2006). "We corroborated the gene expression data by monitoring the expression of several activation markers, including CD25, CD40L, HLA-DR, CD28, CD38, CD44 and CD69, showing no significant modulation when CAR.CD19-T cells are stimulated by the lymphoma DAUDI cells in the presence of INFγ neutralization." (PMID 37296093, 2023).
Obesity (14 papers, 2015 to 2025). Accumulation of substantial excess body fat. "Further, residual iNKT cells from individuals with obesity display an activated profile characterized by increased expression of early (CD69) and late (CD25) activation markers, correlated with the TCR co-receptor, NKG2D." (PMID 41000378, 2025). "On the other hand, circulating NK cells showed decreased surface expression of CD69 in response to obesity." (PMID 39004641, 2024). "Analysing by manifestations, lower levels of baseline activated T CD4+ lymphocytes (CD69) were observed in patients with obesity (1 ± 0.2 vs. 2.4 ± 0.7%; p = 0.076) and metabolic syndrome (1 ± 0.2 vs. 2.2 ± 0.5%; p = 0.039)." (PMID 35165326, 2022). "CD25 and CD69 were significantly upregulated, both in terms of expression levels (MFI) and percentage of positive cells, with 66.13% ± 16.72% CD25+ and 55.01% ± 17.13% CD69+ iNKT cells in individuals with obesity compared to 54.77% ± 17.55% and 43.96% ± 17.54% in lean individuals, respectively." (PMID 41000378, 2025). "Prevention of systemic inflammation due to CD69-positive CD56bright NK cells may represent a promising approach for obesity treatment." (PMID 37832122, 2023). "Previous investigations demonstrated an increased CD69 expression in NK cells in obesity." (PMID 29560551, 2018). "However, during obesity the number of peripheral NK cells increased and they were activated with elevated expressions of CD69 and Granzyme B, but had an impaired ability to respond and eliminate target tumor cells, which was highly related to the severity of obesity." (PMID 32765518, 2020). "In addition, immunophenotyping revealed the increase of the surface expressions of CD44 and CD69 on various cell types, such as CD8+ and CD4 + T-cells, B-cells and macrophages, in animals with obesity." (PMID 39004641, 2024). "Obesity does not impact the ability of Vγ9Vδ2 T cells to upregulate CD69, suggesting that early signaling is preserved in Vγ9Vδ2 T cells from obese subjects." (PMID 25785862, 2015). "Although mean TCR expression level (MFI) was not significantly modulated between individuals with or without obesity, strong negative correlations were observed between TCR levels and both CD25 (R2 = 0.507, p<0.001) and CD69 (R2 = 0.395, p<0.001) expression." (PMID 41000378, 2025).
vitiligo (14 papers, 2018 to 2024). Generalized well circumscribed patches of leukoderma that are generally distributed over symmetric body locations and is due to autoimmune destruction of melanocytes. "Higher levels of CD69+CD103+ TRM were associated with active disease in patients with vitiligo, and importantly, these cells can attract cytotoxic effector CD8 T cells from the blood, which is critical for disease persistence." (PMID 37497226, 2023). "In mouse models, approximately 60–90% of melanocyte-specific CD8+ T cells in vitiligo patients express the Trm cell markers CD69 and CD103, which are highly enriched in skin lesions." (PMID 38779662, 2024). "Two separate groups using different B16 mouse models of vitiligo showed CD8+ TRM identified by CD69+ CD103+ co-expression were critical in mediating vitiligo." (PMID 36466880, 2022). "Studies in vitiligo have shown that the skin surrounding vitiligo lesions is enriched with CD8+ TRM populations expressing CD69 and CD103 during the stable and active phase." (PMID 36439174, 2022). "The numbers of CD69 + CD8 + T cells demonstrated a marked increase in inflammatory vitiligo than common vitiligo, so as to the numbers of CD103 + CD8 + T cells." (PMID 36254016, 2022). "Recent outcomes confirm the presence of auto-reactive CD8+ cells with CD103+CD69+CD49a+ TRM phenotype within the skin of vitiligo patients." (PMID 34839983, 2022). "Immunofluorescence staining show that the numbers of CD69 + CD8 + T cells demonstrated a marked increase in inflammatory vitiligo than common vitiligo." (PMID 36254016, 2022). "Studies on vitiligo showed that vitiligo perilesional skin is enriched with a population of CD8+ TRM expressing both CD69 and CD103, in both stable and active disease stages." (PMID 29967608, 2018). "Moreover, CD69+CD103+ Trm cells are more abundant in the skin of patients with stable vitiligo than in that of patients with active disease." (PMID 38779662, 2024). "CD8+ Trm cell subpopulations expressing CD69, CD103, and CXCR3 were enriched in the epidermal compartments of patients with vitiligo, and they were significantly enriched in stable and active lesions." (PMID 38779662, 2024). "In vitro, T-96 decreased the proliferation, CD69 membrane expression, and IFN-γ, granzyme B, (GzmB), and perforin (PRF) levels in CD8+ T cells isolated from patients with vitiligo." (PMID 37403086, 2023). "In this case, the numbers of both CD69 + CD8 + T cells and CD103 + CD8 + T cells are increased in the inflammatory vitiligo more than common vitiligo." (PMID 36254016, 2022). "Both CD69 + CD8 + T cells and CD103 + CD8 + T cells showed marked increase in inflammatory vitiligo than common vitiligo." (PMID 36254016, 2022). "Additionally, 3D‐Exos markedly attenuated the expression levels of the activation marker cluster of differentiation 69 (CD69), interferon‐gamma (IFN‐γ), and Granzyme B in CD8+ T cells in both the tail skin and peripheral blood of vitiligo mice." (PMID 38887870, 2024). "There were neither significant changes in CD69 expression during therapy nor differences in CD69 expression before therapy in patients who developed vitiligo or not." (PMID 37680638, 2023). "One of the possible functions of BM-resident CD69+ TTE in myeloma is the recruitment of other immune cells from the circulation to the site of disease, as has been demonstrated with resident and circulating memory T cells in a murine vitiligo model." (PMID 33708212, 2021). "Compared to healthy unaffected donor or psoriasis skin, lesional skin from vitiligo patients was shown to be enriched with CD49a+ CD103+ CD8+ and CD69+ CD103± CD8+ TRM cells, independent of disease activity." (PMID 31230406, 2019).
rheumatoid arthritis (13 papers, 2011 to 2026). A chronic, systemic autoimmune disorder characterized by inflammation in the synovial membranes and articular surfaces. "Concomitant with this, CD69 protein expression is increased on infiltrated immune cells at the site of inflammation in immune mediated diseases including systemic sclerosis, rheumatoid arthritis, and SLE." (PMID 41531734, 2026). "In particular CD103+ CD69+ CD8 T resident memory (Trm) cells were found in elevated numbers in previously inflamed joints in rheumatoid arthritis (RA), and shown to initiate flares by recruiting circulating lymphocytes by CCL5 secretion." (PMID 35720379, 2022). "CD69 is known as an activation marker and is expressed on infiltrated leukocytes at inflammatory sites under various chronic human inflammatory diseases, such as rheumatoid arthritis, systemic sclerosis, allergic asthma, and atopic dermatitis." (PMID 35711455, 2022). "CD69 antigen is another mediator found to be involved in the CIA model of rheumatoid arthritis." (PMID 23637839, 2013). "In a study with rheumatoid arthritis (RA) induced in mice, CD69 functioned as regulator of the autoimmune pathology and inflammation by increasing TGF-beta, a cytokine that has been found to be increased in EM/CFS patients." (PMID 29867995, 2018). "Indeed, CD69 is persistently expressed in the infiltrates of leukocytes produced during the course of chronic inflammatory diseases such as chronic hepatitis and rheumatoid arthritis." (PMID 21970554, 2011).
atherosclerosis (12 papers, 2014 to 2025). A disease characterized by the build-up of fatty material and calcium deposition in the arterial wall resulting in partial or complete occlusion of the arterial lumen. "Specifically expand colonic lamina propria Tregs, down-regulate CD69 expression, and promote Treg trafficking via draining lymph nodes and blood to sites of atherosclerosis." (PMID 41169397, 2025). "Deletion of the leukocyte receptor CD69, which regulates Th17 cell/Treg differentiation, increases the Th17 cell/Treg ratio and exacerbates atherosclerosis in mice." (PMID 39817455, 2025). "Remarkably, mice bearing CD69-depleted lymphoid cells that were subjected to a high-fat diet displayed a Th17 cell/Treg imbalance, with exacerbated atherosclerosis." (PMID 39817455, 2025). "A recent study reported that there was a significant downregulation of CD69 mRNA level in peripheral blood leukocytes in the patient with the progression of atherosclerosis." (PMID 35874761, 2022). "Work from our group and others has demonstrated that CD69 is a key regulator of T cell responses, including the balance between proinflammatory Th17 cells and Tregs, which are crucial in the pathogenesis of CVDs such as myocarditis, MI, and atherosclerosis." (PMID 39817455, 2025). "Additionally, expression of CD69 mRNA in peripheral blood leukocytes from a cohort of participants with subclinical atherosclerosis correlates with a slower progression of atherosclerosis." (PMID 39817455, 2025). "We have recently shown that CD69 expression on lymphocytes prevents atherosclerosis progression in mice and that low CD69 levels in PBLs predict subclinical atherosclerosis in asymptomatic individuals after adjustment for traditional cardiovascular risk factors." (PMID 36066993, 2022). "Further, peripheral blood leukocytes from individuals with subclinical atherosclerosis participating in the PESA (Progression of Early Subclinical Atherosclerosis) study displayed reduced CD69 and NR4A expression, supporting their usefulness as early atherosclerotic markers." (PMID 34768801, 2021). "Thus, CD69 expression was considered as an independent predictor of subclinical atherosclerosis." (PMID 35874761, 2022). "Here, in line with our findings, one previous study showed that CD69 as an ox-LDL receptor in T cells and CD69 expression in circulating T cells correlate inversely with subclinical atherosclerosis in the patients." (PMID 35874761, 2022). "The AIM assay showed induction of CD69+CD134+ activation markers on CD4+ T cells, supporting the existence of P210-experienced T cells in humans with atherosclerosis." (PMID 35536648, 2022). "T cell activation receptor CD69 binds to oxidized low-density lipoprotein (oxLDL), inducing the expression of anti-inflammatory NR4A nuclear receptors and modulating inflammation in atherosclerosis." (PMID 35930205, 2022). "Mice lacking CD69 on lymphoid cells fed an atherogenic diet show increased blood Th17/Treg ratio and exacerbated atherosclerosis." (PMID 34768801, 2021). "Our study identifies a new function of CD69 by promoting PD-1 expression in CD4 + T lymphocytes after the engagement with oxLDL that might be responsible for the exacerbated activation state found in the absence of CD69 in the atherosclerosis model." (PMID 35930205, 2022). "Cd69–/– mice exhibit uncontrolled Th17 cell (CD3+CD4+IL-17+) responses and aggravation of multiple autoimmune and inflammatory disease models, including those of the cardiovascular system such as atherosclerosis, myocarditis, and inflammatory dilated cardiomyopathy." (PMID 36066993, 2022). "Additionally, CD69 promotes programmed cell death 1 (PD-1) expression in CD4+ T lymphocytes after engagement with oxLDL, which may be responsible for the exacerbated activation state found in the absence of CD69 in an atherosclerosis model." (PMID 39817455, 2025).
dengue (12 papers, 2016 to 2025). "Interestingly, three markers of NK cell activation, CD69, Fas-L, and Ki-67, were associated with acute dengue in both adult and pediatric patients." (PMID 33067399, 2020). "An earlier study also reported higher percentages of IFN-γ secreting alpha galactosyl ceramide-stimulated iNKT cells in mild dengue patients despite greater percentages of CD69 positive activated iNKT cells in severe dengue patients." (PMID 34335578, 2021). "We found that expression of NK cell activation and functional markers NKG2D, Syk, Fas-L, perforin, and CD69 was higher in adult dengue patients compared with healthy controls and that expression of all these makers was predictive of adult DENV infection." (PMID 33067399, 2020). "Additionally, CD69 is an early activation marker of NK cells, and CD69+CD56dimNK cells are significantly elevated in severe dengue patients even during recovery." (PMID 40680069, 2025). "An absence of statistically significant intra- and inter-group differences in AIM and dextramer analyses except for CD137+CD69+CD8+ at day 90 in the LD group indicates that PepGNP-Dengue induced low-intensity CD8+ T cell responses or involved low percentages of responders at each timepoint." (PMID 38128414, 2024). "Therefore, B cells from dengue patients were stained with anti-Ki-67 and anti-CD69/anti-CD86, two activation markers, and with anti-NS3 to identify infected cells." (PMID 33643283, 2020). "Our group also reported other activation markers such as CD69 and TIA1 as upregulated in mild dengue patients." (PMID 29038620, 2017). "Here, the percentage of CD69+ and CD86+ naïve B cells remained significantly lower in B cells from dengue patients with respect to healthy donors even upon stimulation via BCR and TLR (median CD69+, 16.9 vs 40.2%; P < 0.05) (median CD86+, 26.5 vs 49.2%; P < 0.05)." (PMID 31736948, 2019). "A previous study conducted in paediatric patients with severe dengue in Thailand reported a significantly increased frequency of circulating activated NK cells, characterised by the expression of CD56 and the activation marker CD69, compared to patients with milder forms of dengue." (PMID 41305369, 2025).
Stroke (12 papers, 2016 to 2025). Sudden impairment of blood flow to a part of the brain due to occlusion or rupture of an artery to the brain. "This study also implemented flow cytometry to uncover the inversed association between stroke severity and CD69+CD4+ T cell phenotype." (PMID 39633897, 2024). "The CD69+CD4+ T cell phenotype inversely correlated with stroke severity and was associated with naive and central memory T (TCM) cells." (PMID 33205448, 2021). "Interestingly, this CD69+CD4+ T cell phenotype inversely correlated with stroke severity and was associated with naive and TCM cells." (PMID 33205448, 2021). "Activation of CD8+ T cells has so far only been described in a murine stroke model and only considering the early activation marker CD69." (PMID 41373643, 2025). "Increased frequencies of CD69+ T cells inversely correlated with stroke severity only in the CD4+ compartment." (PMID 33205448, 2021). "Both the CD4+ and CD8+ compartments were rapidly activated by stroke, evidenced by the increased proportion of cells expressing CD69, a marker of early T cell activation." (PMID 33205448, 2021). "Activated CD3+ CD69+ lymphocytes were observed in the CSF mainly at day 6 post-stroke, and in the injured brain parenchyma at day 140 post-stroke." (PMID 32719588, 2020). "We observed a threefold increase in the expression of the activation marker CD69 in circulating iNKT cells of stroke patients compared to both matching Healthy and Hospital controls." (PMID 28154551, 2017). "24h following a stroke, CD69+NKp46+ cell numbers peaked in the brain and remained elevated." (PMID 35359972, 2022). "The frequency of CD69+CD4+ T cells inversely correlated with stroke severity." (PMID 33205448, 2021). "Cell surface expression of CD69 is induced early following T cell receptor (TCR) activation via antigen presentation or by cytokine stimulation, and the presence of circulating CD69+ T cells after stroke suggests that T cell activation had already occurred in peripheral lymphoid tissue." (PMID 27115295, 2016). "In humans, the microRNA (miRNA) profile of peripheral NK cells is altered after stroke and inhibition of miRNA-451a and miRNA-122-5p partially restored CD69 and NKG2D expression, suggesting that targeting miRNAs may alleviate immunosuppression observed after a stroke." (PMID 35359972, 2022). "The increase in CD69+CD4+ cells was restricted to naive and central memory T cells (TCM), which also inversely correlated with stroke severity, while all memory subsets up‐regulated CD69 in the CD8+ compartment." (PMID 33205448, 2021). "After a stroke, the presence of neural antigens was observed in draining lymph nodes close to activated CD3+ CD69+ lymphocytes." (PMID 32719588, 2020). "CD69 was identified as a negative regulator of endothelial VWF release, and in the setting of stroke, its absence resulted in a more severe stroke burden due to increased cerebral thrombosis." (PMID 31921147, 2019). "We found that the activating lymphocyte marker CD69 and IFN-γ were over-expressed in both stroke models compared with sham mice, but more in photothrombosis mice as compared to MCAO mice at 14 days after surgery." (PMID 29246244, 2017).